TFRC (transferrin receptor)
Diseases named in the same sentence as TFRC in open-access papers (continued):
Sharing a sentence is not in itself a finding about the gene and the disease.
cancer (591 papers, 1997 to 2026). A tumor composed of atypical neoplastic, often pleomorphic cells that invade other tissues. "Further analysis of TCGA pan cancer data indicates that TFRC is also associated with immunosuppressive genes." (PMID 40303995, 2025). "Iron metabolism dysregulation is a hallmark of cancer, and TFRC-targeting therapies, such as TfR1 antibodies or ferroptosis-inducing agents, have been explored in preclinical models." (PMID 40496862, 2025). "Although TFRC mRNA and its splice variants have been extensively examined in the contexts of cancer biology and ferroptosis regulation, circRNAs originating from TFRC remain insufficiently characterized." (PMID 40473597, 2025). "TFRC is vital for intracellular iron transport and is linked to ferroptosis, a form of cell death associated with drug resistance in cancer." (PMID 40697100, 2025). "The heatmaps of the correlation between TFRC expression and Cancer associated fibroblast, T cells CD8+, and B cell were shown." (PMID 40303995, 2025). "Transferrin receptor protein 1 (TFRC), a key molecule associated with ferroptosis, has been identified as influencing a broad range of pathological processes in different cancers." (PMID 39131609, 2024). "Logically, increasing TFRC expression in cancer cells was expected to cause an increase in iron loading and promote ferroptosis in malignant cells." (PMID 38221933, 2024). "Higher TFRC gene expression levels were strongly associated with higher cancer T stages and OS events." (PMID 39131609, 2024). "Several cancer genomic and transcriptomic studies have associated increased TFRC expression with the prognosis of various cancers, including OSCC." (PMID 36635327, 2023). "Analysis of a TCGA dataset including all types of cancer suggested that amplification of either the SHARPIN gene or the TFRC gene is associated with DFS." (PMID 37444594, 2023). "Here, analysis of a TCGA dataset including all types of cancer revealed that TFRC was significantly associated with poor prognosis." (PMID 37444594, 2023). "Transferrin-transferrin receptor (Tf-TfR) complex as a major iron uptake pathway is considered a critical factor causing cancer to be sensitive to ferroptosis inducers." (PMID 35309911, 2022). "Quercetin can not only effectively form complexes with iron, but also induce iron deficiency behaviors in cancer cells, such as induction of transferrin receptor-1 and iron regulatory protein-2 expression and decreased ferritin expression." (PMID 36615225, 2022). "The biological activity of ATF is strictly linked to its interactions with transferrin receptors (TfR) that regulates cellular uptake; TfRs are upregulated in the surface of cancer cells and thus can be used as selective target in anticancer drug design." (PMID 33490036, 2020). "TFRC is abnormally expressed in many different types of cancer and has been associated with cancer cell proliferation, apoptosis, migration and invasion/metastasis." (PMID 32867190, 2020). "Cell-to-cell contact can protect cancer cells from ferroptosis by inhibiting the expression of TFRC mediated by transcription factor yes-associated protein 1 (YAP1)." (PMID 33117818, 2020). "Future studies are needed to determine the safety and therapeutic efficiency of correcting cancer-associated aberrations in iron homeostasis by modulating iron availability through the use of miRNA-based transferrin receptor targeting." (PMID 26657500, 2016). "In order to further evaluate the role of transferrin in the cellular uptake of TF-8arm-PEG–DHA NPs, LLC cells and MLE-12 cells were employed as transferrin receptor (TFR) overexpressing cancer cells and TFR deficiency cancer cells, respectively." (PMID 27377918, 2016). "Cancer cells have increased levels of transferrin receptor and lower levels of ferritin, an iron deficient phenotype that has led to the use of iron chelators to further deplete cells of iron and limit cancer cell growth." (PMID 21453502, 2011).
cancer (continued). "Background/Objectives: Overexpression of transferrin receptor (TFR1) is common in cancer and may be associated with inferior treatment outcomes." (PMID 42122198, 2026). "It has also been noted that TFRC expression in cancer cells correlates with susceptibility to ART." (PMID 41188278, 2025). "Moreover, the mechanisms underlying the regulation of TFRC expression in cancer cells are complex and involve various signaling pathways." (PMID 40303995, 2025). "Additionally, we employed advanced bioinformatics techniques to delve into the underlying mechanisms of TFRC and its significant role in immunotherapy, ultimately providing valuable recommendations for enhancing cancer treatment strategies." (PMID 40303995, 2025). "Alteration in the levels of TFRC has been associated with malignant forms of certain cancers." (PMID 38731851, 2024). "In addition, our results show that TFRC is a risk factor in nine cancers, but TFRC is a suppressor of ferroptosis, demonstrating that the promotion or inhibition of cancer by each ferroptosis regulator is affected by many factors." (PMID 34975326, 2022). "In summary, the data presented herein indicate that over-expression of TFRC may be responsible for profound cancer-associated abnormalities in cellular iron metabolism during liver carcinogenesis." (PMID 26657500, 2016). "In addition, since TFRC and ferritin changes appear to be associated with cancer stem cell populations, it may be more appropriate to apply these methods to gene sets designed to interrogate stem cell character rather than iron aberrance alone in GBM." (PMID 27898674, 2016). "The transferrin receptor (TfR) is a target for cancer immunotherapy and also a target protein of GA." (PMID 40900835, 2025). "Cancer cells demand high levels of iron for rapid growth, resulting in upregulated transferrin receptor 1 (TfR1) to increase iron uptake." (PMID 40895556, 2025). "TFRC and HIFs are upregulated in many types of cancer, which correlates with poor prognosis and response to therapy 57,58." (PMID 40083931, 2025). "For example, a large amount of transferrin (Tf) on the surface of cancer cells can bind to transferrin receptors (TfR) naturally present on the surface of EVs." (PMID 40840553, 2025). "To further investigate the impact of TFRC expression on cancer prognosis, we performed univariate Cox regression analysis on overall survival (OS) and disease-specific survival (DSS)." (PMID 40303995, 2025). "Understanding the mechanisms governing TFRC expression and function is crucial for developing therapeutic strategies targeting iron metabolism in cancer and other diseases." (PMID 40303995, 2025). "In cancer cells, due to the large amount of iron required for cell proliferation, the expression of TFRC often increases." (PMID 40303995, 2025). "In the context of cancer, the expression of TFRC on immune cells can significantly affect their functionality and the overall immune response against tumors." (PMID 40303995, 2025). "Transferrin receptor 1 (TfR1) mediates iron import, and cancer cells frequently upregulate TfR1 to meet proliferative demands, inadvertently expanding the ferroptosis-vulnerable labile pool." (PMID 41462716, 2025). "Expression of TFRC was significantly correlated with poor overall survival in all cancer types and its expression was highly upregulated in the majority of cancer types." (PMID 40897687, 2025). "Similar results were also obtained by using the TISIDB database to assess the link between immune cell invasion levels and TFRC levels in 30 cancer types." (PMID 40303995, 2025). "As our understanding of TFRC’s role in cancer biology continues to evolve, it is likely that innovative therapeutic strategies will emerge, offering new hope for improved patient outcomes." (PMID 40303995, 2025).
cancer (continued). "The transferrin receptor‐1 (TFR‐1) is overexpressed in many types of human cancers and, in recent years, several studies have investigated its use as a preferential channel for drug cellular uptake in cancer therapy." (PMID 40550706, 2025). "The transferrin receptor, a membrane protein that binds transferrin, facilitates this high iron concentration typically observed in cancer cells." (PMID 40144390, 2025). "In light of these findings, this study harnessed extensive sample data from various databases, complemented by biochemical experiments, to thoroughly investigate the expression levels and potential clinical applications of TFRC in the context of cancer." (PMID 40303995, 2025). "Cancer cells, among others, enhance iron uptake by upregulating transferrin receptor 1 (TFRC) while simultaneously downregulating ferroportin, the only known iron exporter." (PMID 40663910, 2025). "Tf is a protein recognized for its high binding affinity to the transferrin receptor (TfR), that is often overproduced in cancer cells." (PMID 41304734, 2025). "Recent advancements in nanoparticle technology have facilitated the development of TFRC-targeted gene delivery systems, which can effectively transport therapeutic nucleic acids to cancer cells." (PMID 40303995, 2025). "This system leveragesthe overexpression of transferrin receptors (TfR) on cancer cellsand the elevated levels of hydrogen peroxide (H2O2) within tumor microenvironments." (PMID 40548610, 2025). "Multiple studies report that TFRC knockdown or modulation suppresses PI3K/AKT (±mTOR) signaling in cancer, while CD71 engagement can also elicit AKT activation." (PMID 41375568, 2025). "To further elucidate the role of TFRC in artesunate's anti-cancer mechanism, we evaluated the effects of TFRC knockdown on artesunate-treated MKN45 cells." (PMID 40946428, 2025). "Proteins, including TOP2A, BPI, PSAT1, ANLN, and TFRC, were upregulated in five of the six cancer types." (PMID 41049442, 2025). "Multiple studies have shown that the transferrin receptor (TFRC) is highly expressed in various tumors, and it has been recognized as a cancer biomarker." (PMID 40510157, 2025). "This ‘iron addiction’ phenomenon of cancer cells is reflected in the higher transferrin-receptor 1 (TFR1) expression and enhanced iron uptake leading to increased levels of intracellular, metabolically active iron pool." (PMID 39820815, 2025). "Systematic pan-cancer analysis of unified TCGA datasets across 33 malignancies revealed distinct TFRC expression patterns." (PMID 40303995, 2025). "Among several molecules implicated in cancer biology, CD71, also referred to as transferrin receptor 1 (TfR1), has emerged as a protein of considerable interest." (PMID 41375568, 2025). "In conclusion, the potential of TFRC as a target for both small molecule drugs and gene therapy represents a significant advancement in cancer treatment." (PMID 40303995, 2025). "TFRC is highly expressed in multiple cancers and influences cell proliferation, migration, invasion, and apoptosis by modulating metabolism, inflammation, and iron homeostasis 38-40." (PMID 40302812, 2025). "To assess the role of TFRC in predicting cancer prognosis, we analyzed the relationships between TFRC expression and OS, DSS, and PFI in the TCGA cohort." (PMID 40303995, 2025). "As a result, the transferrin receptor 1 (TFRC) emerged as the most highly expressed cancer-specific receptor." (PMID 39816694, 2025). "Recent research has revealed TFRC’s involvement in various cancer-related signaling pathways, notably the endocytosis pathway, which is significant in trastuzumab resistance." (PMID 38534787, 2024). "A previous study noted that elevated levels of TFRC expression in cancer cells contributed to increased iron uptake, and that degradation of TFRC was essential to reduce essential elements of ferroptosis (unstable iron)." (PMID 38221933, 2024).
cancer (continued). "TFRC is involved in iron metabolism and regulates various genes related to cell death and viral replication, which contribute to cancer aggression." (PMID 39262965, 2024). "GBM cancer stem-like cells demonstrate increased expression of iron uptake proteins transferrin (TF) and transferrin receptor (TFRC), as well as the iron storage protein ferritin." (PMID 38239626, 2024). "We investigated the correlation between the TFRC protein level and clinicopathological characteristics in multiple patients with cancer." (PMID 38419028, 2024). "It has been proven that Mn(II) cations are mainly absorbed and transported by transferrin (Tf) and the transferrin receptor (TfR) system, which is highly expressed in cancer cells." (PMID 38398576, 2024). "Dysregulation of key factors related to iron metabolism, such as lipocalin 2, transferrin receptor (TFR), and ferroportin (FPN), has been linked to unfavorable prognoses and decreased overall survival in different cancer types." (PMID 38602575, 2024). "When the transferrin receptor (TfR) that was overexpressed on the cell surface internalized Tf-Cu, the cytoplasm of cancer cells regained its blue luminescence." (PMID 39128942, 2024). "This protein, known for its cancer cell-targeting properties, has been used in diverse delivery systems due to the frequent overexpression of the transferrin receptor (TfR) in numerous cancer cell types, including in A431 and A375 cell lines." (PMID 39338339, 2024). "In fact, increased expression of the transferrin receptor (TfR) is now well established in a variety of cancers, as is a concomitant downregulation of the iron exporter ferroportin (FPN)." (PMID 38539554, 2024). "The expression of soluble transferrin receptor (sTfR) has also been identified in many malignant tumours." (PMID 38476599, 2024). "Another potential translational application of the HLO1-6H5+ basal cell subset and TFRC proteoform is in the context of cancer." (PMID 39337350, 2024). "Here, we evaluate its targeting mechanism and report that E3 selectively internalizes into cancer cells utilizing a pathway that involves transferrin receptor 1 (TfR 1)." (PMID 37190227, 2023). "They observed targeted drug delivery of doxorubicin, an anti-cancer drug, to cancer cells overexpressing the transferrin receptor." (PMID 37631280, 2023). "Since cancer cells require an impressive amount of iron to grow, the transferrin receptor is highly expressed and presented in various types of cancer cells." (PMID 36795253, 2023). "In fact, cancer cells are characterized by elevated iron content due to a deregulation of iron-related proteins such Transferrin Receptor1 (TfR1), Hepcidin, Ferroportin (FPN) and Ferritins (FtH and FtL, essential for iron storage)." (PMID 36764998, 2023). "Iron uptake in cancer cells is increased through the upregulation of Transferrin/Transferrin-receptor (Tf/TfR), and Lipocalin-2/Lipocalin-2 Receptor (Lcn-2/Lcn-2R) systems and also Divalent Metal Transporter-1 (DMT1)." (PMID 36986466, 2023). "In this study, we report that E3, an aptamer that can target several types of cancer cells and deliver highly toxic drugs to specifically kill cancer cells, targets the human transferrin receptor (TfR)." (PMID 37190227, 2023). "Cancer cells often reduce iron release by upregulating transferrin receptor 1 (TfR1) or inhibiting membrane iron transporter, or increase iron uptake through these mechanisms to sustain cell proliferation." (PMID 38028615, 2023). "If the transferrin receptor expression is normal, the viral particles cannot enter the cell, while the cancer cells require a considerable amount of iron to grow, and the transferrin receptor is expressed in large amounts." (PMID 36795253, 2023).
cancer (continued). "Cancer cells highly express a large number of unique receptors on their surface, such as transferrin receptor 1 (TfR1) and CD44." (PMID 36678599, 2023). "The transferrin receptor (TfR) is necessary for the survival of most cells; however, several reports have indicated that it is often substantially overexpressed in cancer." (PMID 38117806, 2023). "A single chain antibody fragment that recognizes the transferrin receptor (TfRscFv) and specifically targets cancer cells overexpressing TfR is attached to the liposome surface." (PMID 38137175, 2023). "Coincubation of mouse primary antibodies and IgG-M6Pn accelerated the degradation of a neurodegenerative disease target, ApoE4 and a cancer therapeutic target, CD71 (transferrin receptor-1)." (PMID 37592990, 2023). "Targeting TFRC using compounds such as curcumin (one of the most successful chemo-preventive compounds) to intervene with the progression of cancers seems feasible." (PMID 37675227, 2023). "Iron chelators also target iron-related proteins—such as the iron-containing enzyme ribonucleotide reductase (RR) and transferrin receptor (TfR)—and other proteins involved in iron uptake that are overexpressed in various cancers." (PMID 37175072, 2023). "H chains exert ferroxidase activity and have a high affinity for the TfR1 transferrin receptor, over-expressed on the surface of different cancer cell lines." (PMID 36714262, 2023). "In particular, human ferritin displays a key feature that consists in its capability to target specifically the transferrin receptor TfR1, overexpressed on the surface of most cancer cells." (PMID 37883077, 2023). "Abnormal expression of TFRC, a crucial player in iron metabolism, has been verified in various cancers and reported to be over-expressed in peritoneal fluid of women with EM." (PMID 36212136, 2022). "Cancer cells of various origins, compared to healthy cells, are characterized with a overexpression of transferrin receptor 1 (TfR1), which is responsible for binding the Fe from the blood and, therefore, their uptake of Fe is higher." (PMID 35054889, 2022). "Reducing free iron by targeting TFRC is generally considered a therapeutic strategy for various cancers." (PMID 36313765, 2022). "For those reasons, and also due to its extracellular accessibility and ability to internalize, the TFRC has been used as a therapeutic target in cancers." (PMID 36291834, 2022). "The resultant transferrin receptor-targeted nanoparticles proved to selectively bind different cancer cells, with an uptake that was dependent on the levels of surface-exposed receptor." (PMID 35626078, 2022). "Accordingly, expression of TFRC has been reported to positively correlate with sensitivity to ferroptosis inducers, while TFRC knock-out protected RAS-driven cancer cells from erastin-induced ferroptosis." (PMID 35912247, 2022). "When this signaling pathway is antagonized, the protooncogene transcription coactivator YAP will be upregulated, leading to an increase in the key ferroptosis factors ACSL4 and TFRC, thereby inducing ferroptosis in cancer cells." (PMID 35688814, 2022). "Cancer nanotherapies using folate and transferrin receptor mediated nanotherapeutics also allow targeted delivery to tumor cells with significantly reduced damage to nearby cells which were otherwise damaged due to nontargeted conventional chemotherapy." (PMID 35456698, 2022). "They further demonstrated that HPSCC tumorigenesis induced by YTHDF1 is dependent on iron metabolism and regulates transferrin receptor protein (TFRC) expression in this cancer." (PMID 35186927, 2022). "We also observed increased gene expression levels of Transferrin receptor 1 (TfR1) in all four cancer cell lines relative to HThF." (PMID 36371529, 2022). "Early targeted regulation of TFRC expression has been reported as an effective strategy for the treatment of various cancers." (PMID 36052168, 2022).